INS (insulin)
Diseases named in the same sentence as INS in open-access papers (continued):
Sharing a sentence is not in itself a finding about the gene and the disease.
Insulin resistance (continued). "The intraneuronal accumulation of insulin, increased insulin resistance and decreased levels of insulin receptors, are dependent on tau hyperphosphorylation and follow the progression of tau pathology." (PMID 37034173, 2023). "Although the molecular mechanism underlying leptin and insulin resistance in obesity is still incompletely understood, protein-tyrosine phosphatase (PTP) 1B has been demonstrated as a major negative regulator of insulin and leptin sensitivity." (PMID 36649358, 2023). "Insulin resistance (IR) was calculated as Homeostatic Model Assessment for IR and insulin sensitivity (IS) as 1/fasting insulin." (PMID 36673682, 2023). "MUFA induced insulin resistance in the liver and skeletal muscle by increasing serine phosphorylation of the β-subunit of the insulin receptor substrate-1 (IRS-1), inhibiting insulin signaling in the insulin cascade, and promoting insulin resistance." (PMID 37764688, 2023). "Of note, the hyperandrogenism observed in ovaries overexpressing NGF recapitulates the association between insulin resistance and hyperandrogenism in PCOS patients (up to 75% of PCOS patients have impaired insulin sensitivity)." (PMID 36768281, 2023). "Adiponectin treatment promotes adipocyte differentiation and reverses high-fat-diet-induced insulin resistance by increasing insulin-stimulated glucose uptake in muscle and adipose tissue." (PMID 38003291, 2023). "HOMA-IR, a calculation tool that assesses pancreatic B-cell function and insulin resistance via a relationship between fasting plasma glucose and fasting plasma insulin, is another important measurement in glycemic control." (PMID 36901197, 2023). "In order to achieve glucose homeostasis in a healthy pregnancy, circulating insulin is increased to overcome insulin resistance." (PMID 36836658, 2023). "ADIPOR1 is a receptor for adiponectin and triggers a signal transduction pathway that enhances insulin sensitivity and is downregulated in obesity‐induced insulin resistance and T2DM." (PMID 37329278, 2023). "Together, these findings suggest reduced insulin action on metabolism, i.e., increased insulin resistance, despite the lower gain in BW and fat mass." (PMID 36548088, 2023). "Firstly, Se has the characteristics of insulin simulation, which can promote glucose transport, regulate cell glucose utilization, and ions, and reduce insulin resistance." (PMID 37050957, 2023). "T2DM is a metabolic disease primarily characterized by decreasing sensitivity of cells in the body towards the endogenous insulin (insulin resistance) and decreasing insulin secretion, resulting in hyperglycemia." (PMID 36902218, 2023). "T2D is a chronic disease characterized by defects in insulin action (insulin resistance) and secretion." (PMID 37873836, 2023). "We found that HL, in addition to decreasing body fat accumulation, effectively improved insulin resistance by stimulating the hepatic insulin-mediated signaling pathway." (PMID 36742405, 2023). "One of the principal hallmarks of T2DM is insulin resistance (IR), which manifests as decreased tissue insulin sensitivity." (PMID 37762060, 2023). "T2DM is characterized by hyperglycemia resulting from impaired insulin secretion, insulin resistance, or a combination of both." (PMID 37745252, 2023). "This study revealed that gene and protein expression levels of insulin signaling-related factors were elevated in KK/Ay mice, whose glucose intolerance and insulin resistance were suppressed by oral LPS administration." (PMID 36902049, 2023). "DIo (CIR × ISI) estimates β-cell function adjusted for insulin resistance and considers the degree of insulin sensitivity." (PMID 36872321, 2023). "Long-term use of glucocorticoids at high and low doses significantly increases CV risk, with an unfavorable impact on lipid metabolism, obesity, insulin production, insulin resistance, and blood pressure." (PMID 37763669, 2023).
Insulin resistance (continued). "In our current study, we for the first time determined regulatory role of PP1, and more precisely PP1γ, in neuronal insulin signaling and insulin resistance." (PMID 37085815, 2023). "Insulin resistance (IR) is a systemic condition defined as impaired insulin function despite elevated insulin levels (hyperinsulinemia)." (PMID 36677586, 2023). "For instance, insulin resistance, which is defined as a reduced target tissue response to insulin, reduces muscle protein synthesis and increases protein breakdown, resulting in a loss of muscle mass." (PMID 38004100, 2023). "Insulin resistance (IR) is characterized as the decrease in the effectiveness of insulin in glucose utilization or over-secreting of insulin to maintain the stability of blood glucose levels." (PMID 37898776, 2023). "Analysis using indices of insulin sensitivity and insulin resistance calculated by fasting blood glucose and fasting insulin levels would also be helpful." (PMID 36909337, 2023). "Experimental data from animal models suggest that estrogens protect insulin-sensitive tissues from insulin resistance by activating the ERα pathway in females." (PMID 37770988, 2023). "Type 2 diabetes (T2D) is a metabolic disorder characterized by high blood glucose levels due to impaired insulin secretion or insulin resistance." (PMID 37040172, 2023). "Insulin, which would elevate insulin resistance, is actively carried across the blood–brain barrier and activated via cerebral insulin receptors, affecting the energy homeostasis in the brain and interfering the learning and memory." (PMID 37293665, 2023). "Studies using mutant mice with impaired insulin clearance revealed impaired insulin clearance and hyperinsulinemia at 2 months, followed by hepatic insulin resistance at 6–7 months." (PMID 38068822, 2023). "Insulin IRS2-mediated signalling pathways are impaired more by insulin resistance compared to IRS1-mediated signalling pathways." (PMID 36860368, 2023). "Women, classified as the early menarche category, showed elevated levels of fasting insulin, insulin resistance, and central fat accumulation during their adult life." (PMID 38234930, 2023). "The two FFAs that are primarily responsible for insulin resistance and a decrease in insulin sensitivity are diacyglycerol (DAG) and ceramide." (PMID 37446104, 2023). "The significance of insulin in regulating leptin levels and signaling shows the crucial role of leptin in obesity-induced insulin resistance." (PMID 38068941, 2023). "The impairment of insulin’s ability to control glucose metabolism, or insulin resistance, is a major contributor to a range of metabolic and endocrine disorders including T2D." (PMID 37291194, 2023). "The presence of decreased insulin secretion and increased insulin resistance lead to irreversible chronic hyperglycemia, which appears similar to other forms of HNFs/MODY." (PMID 36672242, 2023). "In hepatocytes, overexpression of the Saa receptor, Tanis, led to decreased insulin-stimulated glucose uptake and glycogen synthesis, indicating increased insulin resistance." (PMID 37396595, 2023). "Another study found that TNF‐α can inhibit insulin action and play an important role in obesity‐derived insulin resistance." (PMID 37003602, 2023). "The hepatic insulin sensitivity is normal or slightly reduced, but moderate to severe muscle insulin resistance exists in IGT." (PMID 37402708, 2023). "For instance, a sex difference in glucose metabolism has been described by many studies, which found that women tend to have greater insulin sensitivity than men; moreover, the occurrence of insulin resistance seems to be higher in men." (PMID 37836467, 2023). "The observed insulin resistance in the HFS group indicates the inability of insulin to increase glucose uptake." (PMID 37796781, 2023). "Adipocytokines are secreted by adipose tissues and are known to contribute in defective insulin secretion and action, resulting in peripheral insulin resistance." (PMID 37089941, 2023).
Insulin resistance (continued). "Insulin sensitizers control metabolic abnormalities and improve reproductive outcomes by improving insulin resistance in PCOS women." (PMID 36676074, 2023). "Insulin resistance is clinically defined as a decrease in glucose uptake and utilization capacity by exogenous or endogenous insulin when compared to the normal population." (PMID 36950100, 2023). "Adipokines and cytokines released by hypertrophied adipocytes and hypoxia-related insulin insensitivity promote insulin resistance and, in turn, hyperinsulinemia that affects podocyte function and glomerular barrier selectivity, leading to proteinuria." (PMID 37176781, 2023). "In contrast, during insulin resistance conditions, insulin’s activation of PI3K/AKT signaling is compromised." (PMID 37941908, 2023). "T2DM is a disease in which the development of increasing insulin resistance leads to higher circulating insulin levels, needed to overcome insulin resistance in the tissues." (PMID 37189612, 2023). "The recognition of insulin resistance as a key player in cardiovascular disease highlights the need to study the complex relationships between insulin signaling pathways and the development of atherosclerosis." (PMID 38269234, 2023). "Insulin resistance refers to the decreased sensitivity of cells to insulin, which increases insulin levels in the bloodstream." (PMID 37600709, 2023). "The plasma insulin level was significantly higher in obese mice than that in lean mice, indicating insulin resistance in obese mice." (PMID 37488474, 2023). "Liu and his co-workers demonstrated that the derivatives of Mogroside delivered hypoglycemic results on HepG2 cells and lessened insulin resistance in T2DM rats by improving the gene expression related to insulin signaling." (PMID 36977005, 2023). "Plasma glucose, lipid profile, aminotransferases activity, total antioxidant capacity, malondialdehyde, urea, creatinine, insulin, high sensitivity C-reactive protein, and adiponectin were assessed along with calculation of insulin resistance." (PMID 37500657, 2023). "In obese individuals with high WHtR, excess free fatty acids can impair insulin’s ability to play a role in glucose metabolism and lead to insulin resistance." (PMID 36875460, 2023). "It alleviates insulin resistance, promotes insulin secretion, promotes glucose uptake, induces glycolysis, and inhibits gluconeogenesis in the liver." (PMID 36676074, 2023). "During insulin resistance, higher insulin levels are required to keep glucose at normal levels, and levels of insulin resistance vary." (PMID 37475033, 2023). "The results also showed that dup(G)4CTCACCTGTGG carriers had higher plasma glucose and plasma insulin levels, indicating the involvement of insulin resistance in the onset of T2DM." (PMID 37188647, 2023). "Insulin resistance is one of the hallmarks of obesity, which includes mild inflammation and blockage of several insulin signaling pathways." (PMID 37894813, 2023). "This pyrophosphate reduces insulin sensitivity by preventing the interaction between Akt and PI3K and impairing GSK3β and mTOR signaling pathways, which are both associated with insulin resistance and weight gain." (PMID 37111094, 2023). "The current work shows, for the first time, that kiwi extract prevents obesity-induced insulin resistance through controlling insulin signaling pathway parameters such as PI3K, AKT, and mTOR." (PMID 37762060, 2023). "The peripheral tissues utilize fat as an energy source under muscle insulin resistance, while increased hepatic insulin resistance more readily supplies glucose to the brain." (PMID 37686060, 2023). "This disease, also known as insulin resistance, is generated by disrupting the insulin signaling pathway." (PMID 36823571, 2023). "It was confirmed that they can participate in the development of systemic insulin resistance both directly (by influencing the insulin signaling pathway) and indirectly (by regulating lipid and glucose metabolism)." (PMID 37760906, 2023).
Insulin resistance (continued). "Altered GM composition contributes to changes in insulin levels and insulin resistance by interfering with the insulin signaling pathway." (PMID 37342335, 2023). "Insulin resistance and brain insulin signal transduction defects can accelerate the onset of neurodegenerative diseases by reducing brain metabolism." (PMID 37147888, 2023). "The condition is characterized by a partial or complete inability to use insulin effectively (insulin resistance) despite the presence of functional insulin, thereby leading to hyperglycemia." (PMID 37175192, 2023). "Dual PPARγ/SUR agonists, such as compound 5, can improve insulin sensitivity and stimulate insulin secretion simultaneously, making them an attractive therapeutic option for patients with T2DM who have insulin resistance and decreased insulin secretion." (PMID 38027021, 2023). "Plasma glucose, insulin and the measure of insulin resistance, i.e., homeostatic model assessment of insulin resistance (Homa-IR) changed significantly over the 40 wks of WD feeding." (PMID 37819925, 2023). "Briefly, obesity and insulin resistance are key drivers, the latter triggering an increased flux of circulating free fatty acids (FFAs) from insulin-resistant peripheral adipose tissue to the liver." (PMID 36831649, 2023). "Some studies considered that LPCs' elevation correlates with increased oxidative stress, depression of insulin secretion, and activation of homocysteine-induced insulin resistance." (PMID 40303249, 2023). "Free fatty acid accumulation in skeletal muscles inhibit glucose uptake, reduce fatty acid oxidation and reduce insulin sensitivity which, results in insulin resistance." (PMID 37434784, 2023). "Some studies have assessed several markers such as fasting insulin (FI), fasting glucose (FG), the fasting-glucose-to-insulin ratio (FG/IF) and insulin resistance (IR)." (PMID 37510883, 2023). "In diabetic patients, insulin function is severely impaired, resulting in both insulin resistance and insufficient insulin secretion." (PMID 37764863, 2023). "Insulin resistance is defined as decreased responsiveness (maximal insulin effect) or sensitivity (insulin concentration required for a half maximal response) to insulin’s metabolic actions." (PMID 37964964, 2023). "Insulin resistance has further been reported in healthy pregnancies with a reduction in insulin sensitivity up to 27% in the third trimester, and it was not determined if the reduction in sensitivity in the present study was within normal range." (PMID 37731394, 2023). "Impaired glucose tolerance and insulin resistance are common findings in obese cats, and a 30% decrease in insulin sensitivity has been reported with each additional kg of BW in cats." (PMID 37565085, 2023). "PTP 1B is a tyrosine phosphatase that reverses the IRS-1 phosphorylation of Tyr residues to prevent insulin signaling; therefore, its inhibition can beneficially affect the insulin resistance pathology." (PMID 37298181, 2023). "Type 2 diabetes (T2D) is an increasingly common metabolic disorder attributed to impaired insulin secretion in the setting of relative insulin resistance." (PMID 36814640, 2023). "Free fatty acids (FFA) play a role in the connection between insulin resistance, insulin levels and glucose tolerance." (PMID 36677012, 2023). "IL-6 was positively correlated with obesity; however, the role of IL-6 was controversial, as IL-6 disrupted insulin signaling pathways, resulting in insulin resistance." (PMID 37426418, 2023). "Numerous studies have demonstrated that a moderate reduction in weight can significantly improve insulin sensitivity in various tissues and organs, leading to a reduction in insulin resistance and NAFLD." (PMID 37907845, 2023). "Type 2 diabetes is characterized by elevated glucose levels, impaired glucose tolerance, insulin resistance, defects in the insulin signaling pathway, oxidative stress and mitochondrial dysfunction." (PMID 37104182, 2023).
Insulin resistance (continued). "In rodent models of insulin resistance and impairment in insulin receptor function in the hippocampus, treadmill exercise can rescue this decline in insulin signaling." (PMID 37746149, 2023). "In a prospective observational cohort study, propionyl‐ and isovalerylcarnitine concentrations were positively correlated with triglycerides, C‐peptide, insulin, β‐cell activity, and insulin resistance." (PMID 37264408, 2023). "The APOA1 gene mutation rs670 has been shown to increase HDL-C levels, insulin levels, and the homeostatic model assessment for insulin resistance (HOMA-IR) while simultaneously being associated with decreased insulin resistance." (PMID 37375802, 2023). "Insulin resistance can be defined as a reduced sensitivity to the action of insulin within target tissue." (PMID 36258018, 2023). "This leads to increased liver glycogenolysis, the inhibition of insulin secretion from pancreatic β-cells, and the reduction of glucose uptake in the adipose and skeletal muscle cells (insulin resistance)." (PMID 36982228, 2023). "Coen and Goodpaster reported that type II diabetes and insulin resistance are exacerbated by increased intramyocellular lipid accumulation, affecting how well insulin works." (PMID 37241737, 2023). "Hepatic glycogen storage also stimulates de novo lipogenesis leading subsequently to reduced insulin sensitivity, insulin resistance and glucose intolerance featured in this model." (PMID 37999226, 2023). "In insulin resistance the characteristically higher circulating insulin levels are required to achieve an integrated glucose-lowering response." (PMID 37200851, 2023). "Inflammatory molecules can interfere with insulin signaling in the brain, leading to insulin resistance and impaired glucose metabolism." (PMID 38068904, 2023). "Insulin resistance, characterized by the reduced responsiveness of target tissues to insulin, is a key feature of type 2 diabetes." (PMID 37763235, 2023). "The depletion of Tregs leads to enhanced insulin resistance and impaired insulin sensitivity accompanied by albuminuria and glomerular hyperfiltration." (PMID 36776877, 2023). "Insulin resistance is the outcome of this competition, which lowers the affinity of insulin to IR; thus, insulin resistance together with neuroinflammation and oxidative stress are causes of amyloid-β toxicity and accumulation of neurofibrillary tangles." (PMID 37049607, 2023). "Insulin resistance refers to the decreased sensitivity of target organs to the action of insulin and excessive fatty acids in the circulation, which lead to simple hepatic steatosis, forming the first hit of NAFLD." (PMID 36660274, 2023). "Research has demonstrated that NG ameliorates insulin resistance induced by a high-fat diet through the activation of the insulin pathway (phosphatidyl inositol 3 kinase (PI3K)/protein kinase B (PKB or AKT) and glucose transporters 4 (GLUT4) translocation." (PMID 37372538, 2023). "Considering that cytokines are closely related to insulin resistance, we also performed glucose tolerance tests (IPGTTs) and insulin tolerance tests (ITTs) and found that Angptl8HepKO mice exhibited significantly alleviated insulin resistance." (PMID 37481670, 2023). "Insulin resistance is mainly manifested by decreased insulin sensitivity, which is prevalent in a variety of metabolic-related diseases." (PMID 36983677, 2023). "The associations with increased insulin resistance (HOMA-IR and MATSUDA) and absolute insulin secretion (HOMA-B) remained significant after further adjusting for confounders and weight or body fat (all p ≤ 0.024)." (PMID 37891561, 2023). "Obesity-induced inflammation can lead to insulin resistance in the liver or skeletal muscles, resulting in systemic insulin resistance." (PMID 37569840, 2023). "The impaired insulin sensitivity is possibly due to the development of peripheral insulin resistance." (PMID 36979650, 2023).